EHMT2 (euchromatic histone lysine methyltransferase 2)
Diseases named in the same sentence as EHMT2 in open-access papers (continued):
Sharing a sentence is not in itself a finding about the gene and the disease.
Headache (2 papers, 2022 to 2023). Cephalgia, or pain sensed in various parts of the head, not confined to the area of distribution of any nerve. "Cross-trait gene-based overlap analysis identified 33 genes significantly associated (Pgene-based < 3.85 × 10−6) with migraine and T2D, and 11 genes associated with headache and T2D, with 7 genes (EHMT2, SLC44A4, PLEKHA1, CFDP1, TMEM170A, CHST6, and BCAR1) common between them." (PMID 36292730, 2022). "Among the shared genes, four genes (NEU2, SLC44A4, and EHMT2 on chromosome 6, and STAC3 on chromosome 12) were associated with both migraine and headache." (PMID 36808568, 2023). "Additionally, among the overlapping genes between migraine and headache with glycemic traits, five genes have previously been associated with migraine (THADA, EHMT2, AMBRA1, and SMG6) and headache (ATG13); now, these genes are also implicated in glycemic traits." (PMID 36808568, 2023). "Among these shared genome-wide significant genes between migraine, headache, and glycemic traits, four (NEU2, SLC44A4, EHMT2, and STAC3) were common to both migraine and headache that overlapped more than one glycemic trait." (PMID 36808568, 2023). "Furthermore, five of the 30 genome-wide significant genes overlapping migraine and more than one glycemic trait were the nearest genes to a lead migraine SNP (THADA, EHMT2, AMBRA1, and SMG6) and headache SNP (ATG13)." (PMID 36808568, 2023). "Notably, seven of these genes (EHMT2, SLC44A4, PLEKHA1, CFDP1, TMEM170A, CHST6, and BCAR1) were genome-wide significant for all three traits (migraine, headache, and T2D)." (PMID 36292730, 2022).
Hyperglycemia (2 papers, 2019 to 2025). An increased concentration of glucose in the blood. "Moreover, PRKAG2 (cg20406576) and EHMT2 (cg00210002) are hypomethylated in subjects with hyperglycemia, HOMA-IR ≥2.5 and hypertriglyceridemia." (PMID 30926763, 2019).
hypoxic-ischemic encephalopathy (2 papers, 2022 to 2023). "Also, the expression of EHMT2 could be repressed by the sevoflurane treatment, which exerted a protective effect on neurons in hypoxic-ischemic encephalopathy." (PMID 37529171, 2023).
ischemic stroke (2 papers, 2021 to 2023). A stroke disorder caused by obstruction of blood flow to the brain, due to thrombotic (local blood clot formation) or embolic (due to a blood clot or other material traveling from another site) event. "This research was designed to ascertain the function of euchromatic histone lysine methyltransferase 2 (EHMT2) in ischemic stroke-induced neuronal damage and inflammatory response and its regulatory mechanism." (PMID 37529171, 2023). "Last, more comprehensive investigations about the regulation of other genes by EHMT2/HMOX1 in ischemic stroke are required in our future study." (PMID 37529171, 2023). "Next, we further explored the effect of EHMT2 on ischemic stroke, and functional experiments suggested that EHMT2 was also increasingly expressed in OGD/R-induced BV-2 cells and silencing EHMT2 reduced neuronal damage and restrain inflammatory response." (PMID 37529171, 2023). "First, our experiments in this work were carried out at cellular level and it requires more elaborate animal or clinical experiments to validate whether HMOX1 and EHMT2 also have the same effects in ischemic stroke in vivo." (PMID 37529171, 2023). "This regulatory axis EHMT2/HMOX1 may have a potential as a useful diagnostic and therapeutic biomarker in ischemic stroke." (PMID 37529171, 2023). "Nevertheless, the contribution of EHMT2 to ischemic stroke is rarely studied." (PMID 37529171, 2023). "Afterward, we hypothesized that EHMT2 might affect HMOX1 expression by modulating H3K4Me3 level, thereby participating in the occurrence and development of ischemic stroke." (PMID 37529171, 2023). "Therefore, we speculated that EHMT2 regulated H3K4Me3 to affect the expression of HMOX1, thereby involving the occurrence and development of ischemic stroke, which might provide a promising therapeutic target for the treatment of ischemic stroke." (PMID 37529171, 2023).
kidney cancer (2 papers, 2020 to 2021). Primary or metastatic malignant neoplasm involving the kidney. "In addition, kidney cancers clustered to the right end of groups 1 and 2, which for both groups corresponded to the lowest expression of EHMT2, as well as low CDH10 expression." (PMID 32292512, 2020). "In accordance with this model, CDH10 transcript levels in kidney cancers were found to be strongly reduced regardless of EHMT2 expression." (PMID 32292512, 2020).
mantle cell lymphoma (2 papers, 2021 to 2023). Mantle cell lymphoma is a rare form of malignant non-Hodgkin lymphoma affecting B lymphocytes in the lymph nodes in a region called the ``mantle zone''. "The function of euchromatic histone-lysine N-methyltransferase 2 (EHMT2) has been studied in several cancers; however, little is known about its role in mantle cell lymphoma (MCL)." (PMID 34633777, 2021).
migraine (2 papers, 2022 to 2023). "Among the overlapping genes, four (ADAMTSL4, EHMT2, SUGP1, and MAU2) were associated with migraine, headache, and at least five glycemic traits." (PMID 36808568, 2023).
pancreatitis (2 papers, 2021 to 2024). Inflammation of the pancreas. "To confirm the enhanced tissue damage response during acute pancreatitis observed with loss of Ehmt2, we performed a pairwise analysis of the pancreatitis transcriptional landscape of the Ehmt2 knockout generated either with the Pdx1-Cre (Pdx1-Ehmt2fl/fl) or P48Cre/+ (P48-Ehmt2fl/fl) -driven models." (PMID 38948355, 2024). "Furthermore, our findings suggest that Ehmt2 inactivation also affects nuclear architecture and chromatin organization, potentially influencing gene cluster regulation implicated in pancreatitis pathogenesis." (PMID 38948355, 2024). "Moreover, genetic inactivation of EHMT2 sustains the antagonistic effects on initiation of KrasG12D-driven neoplastic cell growth even in the pancreatitis-associated promotion model." (PMID 34249932, 2021). "While this phenotype indicates that this protein is not essential for organ development, it does underscore a function for Ehmt2 in regulating gene expression networks during pancreatic maturation and pancreatitis." (PMID 38948355, 2024). "We conclude that EHMT2 deletion antagonizes KrasG12D-mediated cell growth even after enhanced stimulation by pancreatitis." (PMID 34249932, 2021). "These networks better illustrate that both, Kras and TNF-α-NFκB pathways were upregulated by pancreatitis to a significantly lesser extent in mice carrying EHMT2 inactivation." (PMID 34249932, 2021). "Here, we delineate the role of Euchromatic Histone-lysine N-Methyltransferase 2 (EHMT2), the enzyme that generates H3K9me, as a downstream effector of oncogenic KRAS during PDAC initiation and pancreatitis-associated promotion." (PMID 34249932, 2021). "In summary, this work identifies EHMT2 as a KRAS-inducible epigenetic regulator which enables this oncogene to exert its effects on growth and inflammation, even when challenged in the pancreatitis-associated promotion model." (PMID 34249932, 2021). "Notably, the effects of EHMT2 inactivation on KrasG12D-induced growth remained under pancreatitis-stimulated conditions, providing further evidence that targeting this epigenomic regulator exerts a dominant effect over the functions of this oncogene." (PMID 34249932, 2021). "Thus, EHMT2 inactivation appears play a role in regulating pancreatitis-enhanced KrasG12D effects, not only through cell growth regulatory pathways, but also in part via immunomodulatory effects, thereby affecting the tumor microenvironment." (PMID 34249932, 2021). "Overall, these data suggest that during the process of pancreatitis-enhanced carcinogenesis by KrasG12D, EHMT2 influences immunomodulatory processes, while reducing EMT, TNF-α signaling via NFκB, and KRAS signaling, which have well-documented effects on growth promotion." (PMID 34249932, 2021).
peripheral nerve injury (2 papers, 2016 to 2021). Injury to a peripheral nerve. "Collectively, DS‐lncRNA negatively regulates Ehmt2 mRNA/G9a expression and participates in G9a‐controlled downstream signaling in injured DRG after peripheral nerve injury." (PMID 34383386, 2021).
tauopathies (2 papers, 2021 to 2023). "Together, these results suggest that inhibition of the elevated EHMT2 can improve spatial and recognition memory in the tauopathy model of AD." (PMID 34547169, 2021).
acute pancreatitis (1 paper, 2024). An acute inflammatory process that leads to necrosis of the pancreatic parenchyma. "The alterations in serum constituents suggest that Ehmt2 deficiency exacerbates inflammation under conditions of acute pancreatitis which can lead to multiple organ dysfunction and failure." (PMID 38948355, 2024). "In summary, loss of Ehmt2 in the pancreatic epithelium results in an augmented response to acute pancreatitis characterized by higher inflammatory cell infiltration, edema, acinar cell damage and death, as well as augmented necrosis." (PMID 38948355, 2024). "Thus, the results from spatial transcriptomics fundamentally confirmed our findings in bulk RNA-seq that Ehmt2 loss in the acinar cell triggers an increased immune infiltrate upon induction of acute pancreatitis." (PMID 38948355, 2024). "In conclusion, our experiments in two complementary mouse models reveal the multifaceted role of Ehmt2 in regulating gene expression and inflammation during acute pancreatitis, exacerbating pancreatic inflammation upon inactivation." (PMID 38948355, 2024). "Congruently, in response to the induction of acute pancreatitis, we show that Ehmt2 inactivation leads to a more aggressive inflammatory response." (PMID 38948355, 2024). "To evaluate the relative contribution of Ehmt2 to the epithelial cell response during pancreatic inflammation, we repeatedly injected Ehmt2+/+ and Ehmt2fl/fl mice with caerulein to induce acute pancreatitis and performed RNA-seq." (PMID 38948355, 2024). "Upon closer examination of individual genes, we observed that the genes in the signature for acute pancreatitis were predominantly overexpressed by a log2 FC of >0.8 in the Ehmt2fl/fl group compared to Ehmt2+/+." (PMID 38948355, 2024). "Here, we investigate the role of Ehmt2 in postnatal murine pancreas development and caerulein-induced acute pancreatitis." (PMID 38948355, 2024). "Of these DEGs, 1,812 were shared between Ehmt2+/+ and Ehmt2fl/fl with acute pancreatitis, consisting of 764 upregulated and 1,048 downregulated DEGs." (PMID 38948355, 2024). "In contrast, samples undergoing acute pancreatitis displayed a distinct separation between the Ehmt2+/+ and Ehmt2fl/fl pancreatic samples." (PMID 38948355, 2024). "Focusing on the gene Spp1, we found 25.7% of spots positive for EMT-like SVG expression in Ehmt2+/+ mice with acute pancreatitis, which notably increased to 45.7% in Ehmt2fl/fl pancreas." (PMID 38948355, 2024). "To delve deeper, we manually examined genes upregulated in acute pancreatitis compared to untreated mice, focusing on the subset that were uniquely activated or further de-repressed during the inflammatory response upon Ehmt2 inactivation." (PMID 38948355, 2024). "Correspondingly, 1,283 were exclusively downregulated during acute pancreatitis in the Ehmt2fl/fl animals compared to 142 in the Ehmt2+/+." (PMID 38948355, 2024). "These collective findings suggest that Ehmt2 helps preserve the epithelial characteristics of acinar and ductal cells in response to pancreatic injury, particularly during instances such as acute pancreatitis." (PMID 38948355, 2024). "In light of recent findings highlighting the enduring epigenetic memory of inflammatory injury in pancreatic acinar cells, the current study’s investigations into Ehmt2 knockout in this specific cell population during acute pancreatitis gains significance." (PMID 38948355, 2024). "Thus, the current study was designed to directly investigate the role of Ehmt2, a robust transcriptional repressor, in experimentally induced acute pancreatitis." (PMID 38948355, 2024). "Interestingly, a large subset of the genes that were found in the Ehmt2+/+ animals, which would constitute the response to acute pancreatitis, overlapped with the Ehmt2fl/fl mice (80% of upregulated and 91% of downregulated genes)." (PMID 38948355, 2024).
acute pancreatitis (continued). "Using a gene signature for acute pancreatitis, we identified a marked increase of overall mean sum expression in Ehmt2fl/fl (3.3) animals in comparison to Ehmt2+/+ (2.6) and an increase of 92% of positive SVGs for the Ehmt2fl/fl animals compared to 83% for the Ehmt2+/+ mice." (PMID 38948355, 2024). "Transcriptional factor enrichment of DEGs by Ehmt2 during acute pancreatitis." (PMID 38948355, 2024). "The induction of acute pancreatitis highlighted immune cell signaling patterns that distinguished Ehmt2+/+ from Ehmt2fl/fl, also revealing an enhanced immune response when Ehmt2 function is lost with the number of markers for immune cells increasing by a total of 16.6%." (PMID 38948355, 2024). "The reproducibility and distinct separation between acute pancreatitis-induced animals with Ehmt2 intact and those with Ehmt2 loss, regardless of the Cre model, present in the PCA are also evident in the heatmap." (PMID 38948355, 2024). "Additionally, we found that the pancreas to body weight ratios increased when Ehmt2 was inactivated during acute pancreatitis, likely resulting from a swollen and enlarged pancreas." (PMID 38948355, 2024). "We found that all genes from the TIS were statistically significant between the Ehmt2fl/fl pancreas compared to the Ehmt2+/+ controls during acute pancreatitis, with a range from 0.34 for Psmb10 as the least log2 FC to 3.48 for Tigit with the most significant change." (PMID 38948355, 2024). "However, the impact of Ehmt2 on the transcriptome during early development and under the inflammatory stressor of acute pancreatitis remains unknown." (PMID 38948355, 2024). "This analysis aimed to identify genes involved in the injury response during acute pancreatitis that are transcriptionally regulated by Ehmt2, independent of the model used." (PMID 38948355, 2024). "PCA demonstrated that animals with intact Ehmt2 clustered together during the acute pancreatitis treatment regardless of the model, Pdx1 or P48Cre/+, and separated from their Ehmt2fl/fl counterparts." (PMID 38948355, 2024).
alcohol dependence (1 paper, 2025). Physical and psychological dependence on alcohol. "We recently showed that the epigenetic regulatory enzyme G9a (also known as euchromatic histone-lysine N-methyltransferase 2 or EHMT2) is downregulated in the nucleus accumbens (NAc) in mice by alcohol dependence produced by the chronic intermittent alcohol (CIE) model." (PMID 40926332, 2025).
Brain atrophy (1 paper, 2021). Partial or complete wasting (loss) of brain tissue that was once present. "A recent analysis observed higher C3 and lower EHMT2 plasma levels related to increasing brain atrophy in MS patients." (PMID 34367251, 2021).
cardiomyopathy (1 paper, 2024). A disease of the heart muscle or myocardium proper. "We consider the regulation of Pip4k2c, Ehmt2, Gper1, Dicer 1, Cul4b, Fyco1, Gn3l and TNNT2 in the context of doxorubicin-induced cardiomyopathy as particularly relevant." (PMID 39285385, 2024).
chronic hepatitis B (1 paper, 2014). "Previous studies showed that single nucleotide polymorphisms (SNPs) in the HLA-DP, TCF19 and EHMT2 genes may affect the chronic hepatitis B (CHB)." (PMID 24465836, 2014).
colon adenocarcinoma (1 paper, 2021). "We identified EHMT2/G9a (Hazard ratio (HR): 2.2, p = 0.0036) and DNMT3A (HR: 1.9, p = 0.047) overexpression to be significantly associated with shorter RFS in colon adenocarcinomas (COAD)." (PMID 33323965, 2021).
cutaneous melanoma (1 paper, 2026). A primary melanoma arising from atypical melanocytes in the skin. "For instance, gain-of-function genetic alterations of EHMT2 in cutaneous melanoma cells can drive tumorigenesis and immune suppression in a T cell-dependent manner." (PMID 41366520, 2026). "Similarly, regulation of T-cell-mediated cytotoxicity by EHMT2 was also observed in the case of cutaneous melanoma." (PMID 41366520, 2026).
diverticular disease (1 paper, 2024). A complex disorder characterised by mucosal outpouchings (diverticulae) of the colonic wall which can become infected and inflamed leading to diverticulitis, perforation and bleeding. "Two GWS genes (EHMT2 and HLA-DRB1) overlapped between T2D, IBD, and diverticular disease." (PMID 38802514, 2024).
female sterility (1 paper, 2025). "The H3K9 methyltransferase EHMT2 (G9a) plays a pivotal role in HR during female germ cell meiosis and depletion of EHMT2 disrupts the completion of DSBs repair, ultimately leading to female sterility." (PMID 40650982, 2025).
foot and mouth disease (1 paper, 2024). A viral infectious disease that results in infection in cattle and swine, has material basis in foot-and-mouth disease virus, which is transmitted by contaminated fomites, or transmitted by ingestion of food contaminated with infected meat or animal products. "In agreement to our results, UNC0638 mediated inhibition of EHMT2 has been shown to induce antiviral response against Foot-and-Mouth disease and Vesicular Stomatitis Virus Infections in bovine cells." (PMID 38277395, 2024).
Hepatitis (1 paper, 2020). Inflammation of the liver.
lentivirus infection (1 paper, 2020). Virus diseases caused by the Lentivirus genus. "The EHMT2 expression level and methylation level of H3K9 were verified by Western blots, and the results showed that the EHMT2 protein level and H3K9me2 were significantly reduced in RAVSMCs after shEHMT2 lentivirus infection." (PMID 32174799, 2020).
lymphoma (1 paper, 2021). A malignant (clonal) proliferation of B- lymphocytes or T- lymphocytes which involves the lymph nodes, bone marrow and/or extranodal sites. "In our results, some of the differentially methylated genes in EHMT2 + MCL cases have also been reported with recurrent genetic alterations in lymphoma, such as ALK, DUSP22, NCOR2, RORA, DLC1, JAG1/2, JAK1, NOTCH4, and CD1938–45." (PMID 34633777, 2021).
malaria (1 paper, 2025). Malaria is a serious and sometimes fatal disease caused by a parasite that commonly infects a certain type of mosquito which feeds on humans. "In addition, we delve into the advancements in the design and synthesis of G9a/EHMT2 inhibitors, which hold promise not only as a treatment for neurodegeneration diseases but also for other conditions, such as cancer and malaria." (PMID 39763018, 2025).
monoclonal gammopathy of undetermined significance (1 paper, 2021). "Levels of EHMT2 expression were also higher in monoclonal gammopathy of undetermined significance (MGUS), and smoldering MM (SmMM) patients than in NPCs." (PMID 33436557, 2021).
oligodendroglioma (1 paper, 2023). A well-differentiated (WHO grade II), diffusely infiltrating neuroglial tumor, typically located in the cerebral hemispheres. "Contrasted with a protective role in oligodendrogliomas, early work on the role of EHMT2 in GBM tumorigenicity was mixed, but with more recent evidence supporting a pro-tumorigenic role." (PMID 37205197, 2023). "Euchromatic histone lysine methyltransferase 2 (EHMT2), also known as G9a, mediates repressive mono- and dimethylation of H3K9 and its expression is associated with improved survival in grade II oligodendrogliomas." (PMID 37205197, 2023).